RNU1-140P (RNA, U1 small nuclear 140, pseudogene)
Gene: Small nuclear RNA gene on chromosome 5 (104,098,874 to 104,099,038, forward strand). Ensembl gene ENSG00000201910.
Homologues: Orthologues: chimpanzee U1 (99% identical), macaque U1 (88% identical), guinea pig U1 (79% identical), dog U1 (76% identical), pig U1 (72% identical), rat LOC120097302 (72% identical), dog U1 (69% identical), mouse Gm22054 (61% identical), rabbit U1 (61% identical). Paralogues in human: RNU1-89P (84% identical), RNVU1-32 (84% identical), RNU1-1 (84% identical), RNU1-2 (84% identical), RNU1-27P (84% identical), RNU1-28P (84% identical), RNU1-3 (84% identical), RNU1-4 (84% identical), RNVU1-18 (84% identical), RNVU1-28 (84% identical), RNVU1-29 (84% identical), RNVU1-31 (84% identical), and 133 more.